EGF (epidermal growth factor)
Diseases named in the same sentence as EGF in open-access papers (continued):
Sharing a sentence is not in itself a finding about the gene and the disease.
osteoarthritis (5 papers, 2021 to 2023). A noninflammatory degenerative joint disease occurring chiefly in older persons, characterized by degeneration of the articular cartilage, hypertrophy of bone at the margins and changes in the synovial membrane. "The content of TNF-α, EGF and sAPO-1/Fas in Helicobacter pylori-positive gastroduodenopathies caused by NSAIDs in patients with osteoarthritis in the dynamics of treatment 1 month (M ± m)." (PMID 34104240, 2021). "This evidence point to the role of the EGF pathway in osteoarthritis (OA), as confirmed by several knockout murine models." (PMID 34955078, 2022). "Therefore, a sustained and localized delivery of EGF in a spatial-temporally fashion is needed as a potential treatment of osteoarthritis." (PMID 34603477, 2021). "Furthermore, PRF contains more growth factors than PRP, including IGF-I, FGF, EGF, and PDGF, which play important regulatory roles in collagen synthesis and could prevent the change in the ECM molecule caused by osteoarthritis to some extent." (PMID 38144541, 2023). "Milk fat globule-epidermal growth factor (EGF) factor 8 (MFG-E8), as a necessary bridging molecule between apoptotic cells and phagocytic cells, has been widely studied in various organs and diseases, while the effect of MFG-E8 in osteoarthritis (OA) remains unclear." (PMID 34031369, 2021).
pituitary adenomas (5 papers, 2008 to 2024). "In mammals, expression of EGF and ErbBs have been detected in both the normal pituitary and pituitary adenomas, and the EGF/ErbB system has been explored in both pituitary hormone regulation and pituitary cell proliferation/differentiation." (PMID 30587833, 2018). "In summary, IL‐6, CCL2, EGF/EGFR, VEGF/VEGFR, and other cytokines are expressed in pituitary adenomas and are generally related to their aggressiveness, occurrence, and development." (PMID 38738958, 2024). "Studies have confirmed that EFGR was overexpressed in recurrent growth hormone‐secreting pituitary adenomas and invasive silent subtype III adenomas, suggesting that EGF/EGFR expression may be related to the recurrence and aggressiveness of pituitary adenomas." (PMID 38738958, 2024). "Tumor sphere formation methodology with EGF, FGF, and B-27 supplement seems to be usable for gaining pituitary adenoma stem/progenitor cells that might be capable of tumor formation and differentiation into hormonal cells." (PMID 27340409, 2016). "Pituitary adenomas may over-express certain growth factors or their receptors such as FGF-2, EGF, TGF-α, EGF-R, Notch-3, FGF-R1, and VEGF." (PMID 18081553, 2008). "In addition, EGF is expressed in functional and nonfunctional pituitary adenomas, with higher expression in more aggressive tumor subtypes." (PMID 37563740, 2023).
pressure ulcers (5 papers, 2017 to 2024). "All of these approaches are based on recombinant human epidermal growth factor (rhEGF), effective in treating DFUs, pressure ulcers, vascular ulcers, and chronic leg ulcers." (PMID 34361451, 2021).
psychosis (5 papers, 2013 to 2024). "On the other hand, in both study groups, the statuses of psychosis, anthropometric and metabolic parameters were comparable, limiting the potential impact of these co-variables on EGF levels." (PMID 38004423, 2023). "Finally, fentanyl reduced the expression of NMDA receptors and dopamine receptors whilst elevating epidermal growth factor (EGF) levels, which was suggested as a mechanism whereby such neural changes may result in the development of psychosis." (PMID 39453110, 2024).
renal failure (5 papers, 2019 to 2025). "It was found that BM-MSCs can significantly improve renal histology and systemic homeostasis by upregulating the serum levels of anti-inflammatory cytokines, such as epidermal growth factor (EGF) and IL-10, thus prevent renal insufficiency and glomerular sclerosis." (PMID 33221823, 2020).
systemic lupus erythematosus (5 papers, 2013 to 2022). An autoimmune multi-organ disease typically associated with vasculopathy and autoantibody production. "And as such we speculate that the effect may be implemented by the OMRGs, including PHLPP2 and EGF, as well as three pathways (alcoholism, systemic lupus erythematosus, and proteoglycans in cancer) through which the OMRGs may be response to OM." (PMID 29887852, 2018). "Baseline urine MCP-1 and EGF levels in systemic lupus erythematosus (SLE) patients and controls (total n = 101) were compared, and levels were correlated with clinicopathological findings and subsequent response to treatment." (PMID 35271583, 2022). "VEGF, epidermal growth factor (EGF), FGF and IL-18 have been found in sera of patients affected by systemic lupus erythematosus." (PMID 23725043, 2013).
venous ulcers (5 papers, 2017 to 2025). "There is some evidence of mild to complete degradation in venous ulcer wound fluid of proteins such as vitronectin and EGF; therefore, the lack of response to individual topical growth factors for VLUs may be due to the breakdown of the growth factors by proteases in the chronic wound environment." (PMID 29703712, 2018).
age-related macular degeneration (4 papers, 2010 to 2025). Age-related loss of vision in the central portion of the retina (macula), secondary to retinal degeneration. "Platelets produce platelet-derived GF (PDGF), IGF-1, TGFβ, VEGF, bFGF, EGF, platelet-derived angiogenesis factor (PDAF), and thrombospondin (TSP), and several authors have used them in eye diseases such as glaucoma, age-related macular degeneration (AMD), and RP." (PMID 33066211, 2020).
anaplastic thyroid cancer (4 papers, 2005 to 2025). "Likewise, DEL-22379 displays activity in other ERK2 dimerization-related functions, such as in memory reconsolidation and synaptic plasticity, inhibiting hippocampal ERK2 dimerization in EGF-stimulated in vivo results; or in anaplastic thyroid cancer induced by BRAF mutation." (PMID 41373638, 2025). "Our previous studies have demonstrated that epidermal growth factor (EGF) can induce cell migration through the induction of cysteine-rich protein 61 (Cyr61) in human anaplastic thyroid cancer (ATC) cells." (PMID 25742642, 2015). "Specific EGFR stimulation with epidermal growth factor showed significant phosphorylation of ERK1/2 and Akt, and resulted in marked growth stimulation in an anaplastic thyroid cancer cell line, which highly expressed EGFR." (PMID 15785737, 2005).
androgenetic alopecia (4 papers, 2019 to 2023). "Its mechanism of action in improving androgenetic alopecia is potentially associated with the increased expression of EGF, FGF5, and FGF7." (PMID 33353178, 2020).
autoimmune disease (4 papers, 2016 to 2025). A disorder resulting from loss of function or tissue destruction of an organ or multiple organs, arising from humoral or cellular immune responses of the individual to their own tissue constituents. "It has also been reported that nitration of EGF and TNFα makes these molecules strongly immunogenic, and that the presence of nitrotyrosine-modified proteins is associated with several autoimmune diseases." (PMID 26700624, 2016). "Moreover, growth factors, such as vascular endothelial growth factor (VEGF) and epidermal growth factor (EGF), when overexpressed, facilitate increased autoimmune diseases activity and tumorigenesis." (PMID 33723630, 2021).
cleft palate (4 papers, 2013 to 2022). Cleft palate is a fissure type embryopathy that affects the soft and hard palate to varying degrees. "In humans, the cleft palate has been associated with polymorphism in TGFA gene, encoding for TGF-α, thus linking this condition to the EGF pathway." (PMID 34955078, 2022). "In a previous study, a disruption in normal expression of EGF was found correlated with improved proliferation and differentiation of medial cells in developing palate and resulted in cleft palate in rat embryo." (PMID 33456767, 2020). "We selected eight genes associated with cleft palate (i.e., fibroblast growth factor receptor (FGFR), epidermal growth factor (EGF), PAX9, and tumor protein p63 (TP63))." (PMID 31480549, 2019). "Collagen and matrix metalloproteinase (MMP) production is known to be induced by EGF signaling and crucial for development of Meckel's cartilage; defects in this entire pathway can obviously lead to underdeveloped mandible and cleft palate." (PMID 23516636, 2013).
demyelination (4 papers, 2013 to 2025). "In in vitro demyelination models, EGF has also been observed to promote the remyelination and expression of MBP and CNPase and appears to be more efficient for this process than other growth factors such as FGF and PGDF." (PMID 35330085, 2022). "In a Lysophosphatidylcholine (LPC)-induced demyelination model, intraventricular infusion of epidermal growth factor (EGF) dramatically promoted the proliferation and migration of SVZ NSPCs as well as their differentiation into oligodendrocytes." (PMID 24421755, 2013).
dengue (4 papers, 2013 to 2023). "Decreased levels of EGF, analyzed in samples collected in the same dengue outbreak, were previously associated with severe illness (shock cases)." (PMID 28586397, 2017). "Previous dengue infection was associated with increased concentrations of IL-17A and IL-1β but decreased concentrations of epidermal growth factor (EGF), and IL-8 compared to dengue-naive individuals." (PMID 37943879, 2023). "When these cytokines were determined in patients classified according to the occurrence of plasma leakage and shock, levels of RANTES and EGF were significantly decreased in patients with shock compared to patients with uncomplicated dengue." (PMID 23717702, 2013). "Alternatively, it is believed that the reduced levels of PDGF and EGF in dengue patients could reflect their consumption in the endothelial repair process." (PMID 36297236, 2022). "Thus, increased levels of VEGF, GM-CSF, G-CSF, TGF-β, and HGF, as well as decreased levels of PDGF and EGF, were observed in severe dengue in most studies." (PMID 36297236, 2022). "Alternatively, the reduced EGF levels in severe dengue patients (Dengue Hemorrhagic Fever- DHF) might reflect its consumption in the endothelial repair process." (PMID 28586397, 2017). "A total of six studies analyzed EGF, and five found decreased levels in dengue patients; most of them were severe dengue compared with nonsevere dengue and/or healthy controls, including two studies in children only." (PMID 36297236, 2022).
diabetic retinopathy (4 papers, 2013 to 2021). "Only one study revealed higher EGF serum concentration in a cohort of people with diabetic retinopathy as compared with controls without retinopathy." (PMID 31936869, 2020). "MG migration was studied in response to concentration gradients of EGF and VEGF, two key factors for diabetic retinopathy, while ShC migration was examined in response to gradients of BDNF, critical to nerve regeneration and guidance in peripheral neuropathies." (PMID 31370352, 2019).
ependymoma (4 papers, 2000 to 2023). A WHO grade II, slow growing tumor of children and young adults, usually located intraventricularly. "FGF and EGF supplements in our improved media were also demonstrated to be potent pro-oncogenic factors in ependymoma by autocrine or paracrine actions." (PMID 37508868, 2023).
esophageal adenocarcinoma (4 papers, 2010 to 2022). A malignant tumor with glandular differentiation arising predominantly from Barrett mucosa in the lower third of the esophagus. "The G/G genotype of the EGF +61A/G polymorphism has been observed to correlate with a greater risk of esophageal adenocarcinoma and increased levels of EGF in gastroesophageal reflux disease patients compared with A/A or A/G." (PMID 24945674, 2014). "Given that elevated blood EGF levels are linked with several toxicities, such as esophageal adenocarcinoma and non-small lung cancer, rhEGF eyedrops may be delivered without causing systemic toxicity." (PMID 36355484, 2022). "However, the role of the EGF/EGFR pathway in the development of gastroesophageal reflux disease (GERD) and its complications (reflux esophagitis (RE), Barrett's esophagus (BE), and esophageal adenocarcinoma (EAC)) remains unclear." (PMID 36092955, 2022).
esophagitis (4 papers, 2018 to 2025). An acute or chronic inflammatory disease affecting the esophageal wall. "Reduced severity of esophagitis was associated with downregulation of EGF, IL-16, CCL3, CCL7, and prolactin, suggesting decreased inflammation." (PMID 39808500, 2025). "The exogenous administration of EGF prevented the increased severity of esophagitis in rats after sialoadenectomy." (PMID 35564692, 2022).
Glomerular sclerosis (4 papers, 2012 to 2025). Accumulation of scar tissue within the glomerulus. "Furthermore, both UMOD and EGF were significantly negatively correlated with tubulointerstitial fibrosis, and EGF was significantly negatively correlated with glomerulosclerosis." (PMID 39835101, 2024). "Glomerulosclerosis also exhibited a negative association with EGF, and tubulointerstitial fibrosis was negatively correlated with both UMOD and EGF." (PMID 39835101, 2024).
heart failure (4 papers, 2015 to 2024). Inability of the heart to pump blood at an adequate rate to meet tissue metabolic requirements. "Among epidermal growth factor inhibitors, erlotinib and gefitinib can lead to coronary artery events; however, afatinib and osimertinib can be associated with the development of heart failure." (PMID 32349387, 2020).
Hyperinsulinemia (4 papers, 2017 to 2025). An increased concentration of insulin in the blood. "An increase in EGF during marked hyperinsulinemia could also be associated with the onset of lamellar damage initiated by insulin, with EGF initiating a wound healing response as postulated above." (PMID 31805097, 2019). "Hyperinsulinemia is associated with the stimulation of insulin-like growth factor (IGF) and epidermal growth factor (EGF) which activate the mTor-Akt pathway." (PMID 33440853, 2021). "Further, the EGF concentrations during acute laminitis (~46 hour samples) did not correlate with insulin concentration measured at the same time in these horses (r2 = -0.32; P = 0.50), which was not unexpected given the marked exogenous hyperinsulinemia." (PMID 31805097, 2019).
injury (4 papers, 2019 to 2025). Damage inflicted on the body as the direct or indirect result of an external force, with or without disruption of structural continuity. "A previous study investigated the striatal neurogenesis and subsequent functional recovery following chronic infusion of BDNF and Epidermal Growth Factor (EGF) in an animal model of hypoxic neonatal brain injury." (PMID 40895108, 2025). "Moreover, the significant association of postoperative levels measured within 6 hours of surgery with AKI also makes urinary EGF a promising candidate marker of early kidney injury, even before a detectable rise in serum creatinine." (PMID 33974569, 2021).
kidney cancer (4 papers, 2010 to 2023). Primary or metastatic malignant neoplasm involving the kidney. "Pathways such as VEGF, EGF and mTOR are known to be one of the major mechanisms of tumorigenesis including kidney cancer." (PMID 36286049, 2022). "Recent findings indicate that EGF signalling is an important mediator of bone metastasis in breast, prostate and kidney cancers." (PMID 20010942, 2010). "Most kidney cancer patients overexpress VEGF, EGF, PDGF, TGF2a, and other growth factors due to VHL gene mutation and abnormal growth of tumor tissues resulting in HIF-related transcriptional activation." (PMID 35035522, 2022).
lung squamous cell carcinoma (4 papers, 2018 to 2025). "In addition, the GRP78-targeted subtilase cytotoxin catalytic subunit is fused with epidermal growth factor (EGF-SubA) to make a variety of cancer cells sensitive to photodynamic therapy (PDT), including human squamous cell lung cancer SW-900." (PMID 33743739, 2021).
mastitis (4 papers, 2009 to 2025). Inflammation of breast tissue during lactation or postpartum due to an obstructed duct or infection. "Evidence for the presence of EGF in the bovine mammary glands stems from a single study that reported elevated expression for both EGF and TGFA mRNA during mastitis." (PMID 37219601, 2023). "Interestingly, the transcription of both EGF and TGFA was increased during mastitis." (PMID 37219601, 2023).
melasma (4 papers, 2023 to 2025). "The efficacy of PRP in melasma has also been associated with growth factors, such as TGF‐β1, TGF‐β2, PDGF, and EGF, which reduce melanogenesis through various signal transduction pathways." (PMID 39175423, 2024). "It is worth noting that the administration of epidermal growth factor (EGF) in horses with corneal ulcers has been associated with adverse effects such as corneal edema, vascularization, melanosis, and scarring." (PMID 38071242, 2023). "While the fusion of EGF to CCP can enhance its transdermal ability, the effects of the fusion protein on skin repair, melasma, whitening, and anti-aging are poorly explored." (PMID 39308805, 2024). "Additionally, EGF may inhibit prostaglandin-E2 (PGE2) expression and decrease tyrosinase enzyme activity; both are involved in the mechanism of melanin production and potentially contribute to the reduction in melasma or hyperpigmentation." (PMID 41149049, 2025).
meningitis (4 papers, 2020 to 2023). A disorder characterized by acute inflammation of the meninges of the brain and/or spinal cord. "The CIMAvax-EGF vaccine comprises of a chemical conjugate of EGF with the p64 protein of meningitis B bacteria." (PMID 35047986, 2020). "Markedly, all vital biotargets of calycosin-anti-meningitis are identified, and at least some of new anti-meningitis targets may include EGF, ATM, CASP8." (PMID 33031061, 2020). "More significantly, all vital biotargets of calycosin-anti-meningitis were eventually identified, including EGFR, TNF, EGF, ATM, ESR1, CASP8, NGF." (PMID 33031061, 2020). "However, so far, there are no scientific reports regarding the associations between EGF, ATM, CASP8 and meningitis." (PMID 33031061, 2020).
mood disorder (4 papers, 2021 to 2026). A cognitive disorder a disturbance in which the person's mood is hypothesized to be the main underlying feature. "Constantly, higher EGF was detected in depressed, hypomanic/manic, and euthymic states compared to healthy controls, making EGF a potential biomarker of mood disorders, especially considering high statistical power." (PMID 34575175, 2021). "The main finding of our study is a disease-dependent significant elevation of EGF in adolescents with mood disorders." (PMID 34575175, 2021). "Recent studies have suggested that elevated levels of EGF may serve as a candidate biomarker for mood disorders, highlighting its potential relevance in psychiatric conditions." (PMID 40611827, 2025). "The main finding of our study is a disease- not state-dependent significantly elevated EGF level in adolescent patients with mood disorders compared to healthy controls." (PMID 34575175, 2021). "Progeny who converted to mood disorder had higher EGF than those with no disease before disease onset, though both groups had lower EGF than healthy controls." (PMID 34575175, 2021). "According to the neurodevelopmental and neuroimmunological hypotheses of mood disorders, we analyzed serum levels of brain-derived neurotrophic factor (BDNF), proBDNF, epidermal growth factor (EGF), migration inhibitory factor (MIF), stem cell factor (SCF), and correlations with clinical factors." (PMID 34575175, 2021).